IL17A (interleukin 17A)
Diseases named in the same sentence as IL17A in open-access papers (continued):
Sharing a sentence is not in itself a finding about the gene and the disease.
psoriasis (continued). "Psoriasis patients with higher levels of Th17 cells and IL‐17A are more easily subjected to developing depression." (PMID 39660880, 2024). "IL-17A, a key player in AD and psoriasis pathogenesis, negatively regulates autophagy and promotes inflammatory responses." (PMID 38606161, 2024). "The IL-17A-degrading co-assembly has been applied in an imiquimod-induced psoriasis mouse model, where it decreases IL-17A levels in the skin lesion and alleviates psoriasis-like inflammation." (PMID 38396109, 2024). "Three biologic agents sanctioned by the FDA for psoriasis treatment operate through this pathway, including two monoclonal antibodies with high IL-17A affinity: secukinumab and ixekizumab." (PMID 39311381, 2024). "Imiquimod (IMQ)-treated wild type (WT) and T-cell receptor delta chain knock-out (Tcrd−/−) mice were used to investigate the correlation between IL-17A and abnormal changes in LCFAs in psoriasis patients." (PMID 38185620, 2024). "For example, glutamine metabolism was upregulated in IL-17+ γδ T cells during psoriasis, promoting acetylation of the Il17a promoter and increasing IL-17 production." (PMID 38397462, 2024). "The neolipid antigens were subsequently recognized by lipid-specific CD1a-reactive T cells and induced the production of IL-22 and IL-17A in psoriasis patients." (PMID 38481799, 2024). "A lot of clinical trails and real-world researches have demonstrated anti-IL-17A treatment has achieved remarkable effects in psoriasis." (PMID 38695018, 2024). "Particularly, among activated T cells, Th1 cells produce IFN-γ, which activates macrophages, and Th17 cells release IL-17A, IL-17E, IL-17F, and IL-22, which play a role in the pathogenesis of psoriasis." (PMID 39765869, 2024). "Both dendritic cells and keratinocytes in psoriasis revealed an overproduction of IL-23 in Extracellular Immunity, subsequently activating Th17 cells in the dermis to generate IL-17A and IL-22." (PMID 38612783, 2024). "The biomarkers IFN-γ, IL-13, IFN-γ/IL4, IFN-γ/IL13, IL-17A/IL-4, and IL-17A/IL-13 are representative of the effectiveness of psoriasis treatment." (PMID 38791078, 2024). "Psoriasis is largely driven by T helper (TH) 1 (TH1) and TH17 cells with the involvement of IL-17A, TNF-α and IL-22, whereas AD is associated with infiltration of TH2 cells in particular." (PMID 38251799, 2024). "Beyond psoriasis, the dysregulation of IL-17A has broader implications in various inflammatory and autoimmune diseases." (PMID 38892253, 2024). "In turn, this analysis compares the PD and biologic effects of blocking IL-23 with those of IL-17A in patients with psoriasis." (PMID 39224116, 2024). "IL-17RA deletion, specifically in keratinocytes, significantly reduces dermatitis, emphasizing its critical role in IL-17A-mediated neutrophil attraction and psoriasis development." (PMID 38892253, 2024). "In order to better understand the mechanisms by which Clobetasol- and Tacrolimus-mediated signaling repress psoriasis in our model, we examined the mRNA expression of IL-17a and IL-17f that are known potent cytokines in psoriatic plaques." (PMID 39273201, 2024). "Apart from IL-17A inhibitors, brodalumab, targeting IL-17RA directly, has shown efficacy in psoriasis treatment." (PMID 39311381, 2024). "IL-17A, produced by T cells and initially discovered in 1993, plays a crucial role in psoriasis by stimulating keratinocytes to secrete chemokines and other mediators." (PMID 39584990, 2024). "Suginumab, a fully human monoclonal antibody that selectively inhibits IL-17A, is approved for the treatment of psoriasis." (PMID 39559368, 2024). "Th17-derived proinflammatory cytokines, such as IL-17A, IL-17F, and IL-22, are critical in the development of psoriasis." (PMID 39717896, 2024). "The use of secukinumab against IL-17A is registered as a treatment of psoriasis, psoriatic arthritis, and ankylosing spondylitis." (PMID 38672221, 2024).
psoriasis (continued). "These two cytokines have synergistic/cooperative effects on one another, and clinical trial data for bimekizumab, a biologic with dual IL-17A and IL-17F inhibition, has achieved high rates of Psoriasis Area and Severity Index (PASI)-100 clearance." (PMID 38627868, 2024). "The treatment of keratinocytes with psoriasis-promoting cytokines IL17A/TNFα strongly changed the transcriptome." (PMID 39490928, 2024). "Conversely, blocking the inflammatory factors TNF, IL-23, IL-17A, or the corresponding receptor IL-17RA has been shown to be effective in the treatment of psoriasis." (PMID 38255845, 2024). "It reproduces several aspects of psoriasis including acanthosis and parakeratosis, neutrophil infiltration in the epidermis, and activation of the IL-23–IL-17 axis resulting proliferation of IL-17A-producing CD4+ T cells in the lesional skin." (PMID 38312837, 2024). "In psoriasis treatment, in addition to agents that inhibit IL-17A, agents that inhibit both IL-17A and IL-17F have been used, and both have shown marked efficacy in skin conditions." (PMID 39519167, 2024). "Recent clinical studies have shown that therapy with bimekizumab, a dual IL-17A and IL-17F neutralizing antibody, resulted to pronounced clinical responses in patients with psoriasis and psoriatic arthritis." (PMID 39011515, 2024). "In psoriasis, even in remission, they become a source of important inflammatory cytokines such as IL-17A and IL-22." (PMID 39063202, 2024). "Although biological therapies such as TNF inhibitors and IL-17A inhibitors are already widely used for the treatment of psoriasis and PsA over the past two decades, only very little is known about their effects on the entire immune system long-term." (PMID 38673054, 2024). "Investigations have noted IL-17A as the cytokine with the greatest biological activity, exhibiting the highest concentration in psoriasis." (PMID 39311381, 2024). "The inflammatory cytokines, TNF-alpha (Tumor Necrosis Factor-alpha) and IL-17A (Interleukin-17A), are related to psoriasis and have been pointed out to damage the autophagy function of keratinocytes." (PMID 38791423, 2024). "Again, pathway analysis for both groups suggested a residual psoriasis signature and IL-17A signaling in fibroblasts." (PMID 38892277, 2024). "Bimekizumab, which suppresses both interleukin (IL)‐17A and IL‐17F, has recently been approved as a biologic for psoriasis." (PMID 38482898, 2024). "Compared with the control group, Rorc-tdTomato+IL17A+ cells also increased significantly in psoriasis mice." (PMID 38566145, 2024). "The first, secukinumab, is a humanized IgG1 monoclonal antibody that selectively binds to and neutralizes IL-17A with remarkable efficiency in psoriasis and PsA." (PMID 38793117, 2024). "The IL-17 cytokine family comprises six isoforms (IL-17A to IL-17F), with IL-17A being the most extensively studied in the context of psoriasis." (PMID 38541607, 2024). "The hyperactivity of the IL17A pathway in our study results in overstimulation of inflammatory responses, typical of conditions like psoriasis, where excessive IL17 signaling leads to chronic skin inflammation." (PMID 39911581, 2024). "In psoriasis, biological treatments targeting Interleukin (IL)-17A, a key cytokine, have shown promise in reducing cardiovascular risks." (PMID 39519167, 2024). "Using this method, this study compared the differences in LCFA metabolism between healthy individuals and psoriasis patients and examined the changes in LCFAs in each psoriasis patient receiving pretherapy and posttreatment with anti-IL-17A mAb." (PMID 38185620, 2024). "In the case of the psoriasis model, a TH17-associated cytokine cocktail (IL-17A and IL-22) was used, and in the case of the AD model, a TH2-associated cytokine cocktail (IL-4, IL-5 and IL-13) was used." (PMID 38251799, 2024).
psoriasis (continued). "In a study evaluating the treatment of psoriasis with IL-17A and TNF-α inhibitors, it was observed that the differential expression of the protein TYMP before and after treatment was significant." (PMID 39480805, 2024). "In parallel, the mRNA expression levels of psoriasis-related cytokines, such as IL-17A, IL-23, IFN-γ and IL-22 greatly increased in immune-related skin reactions to anti-PD-1." (PMID 38495872, 2024). "During extended treatment with anti-IL-17A mAb, LCFAs in psoriasis patients gradually decreased, consistent with changes in the PASI scores before and after treatment." (PMID 38185620, 2024). "In this case, we presented a patient who experienced a swift progression of condyloma acuminatum on the genitals during psoriasis treatment with secukinumab, a human IL-17A antagonist." (PMID 38813385, 2024). "Clinical efficacy of anti-IL-17A monoclonal antibody (mAb) treatment in psoriasis patients has been demonstrated." (PMID 38185620, 2024). "The activation of cDCs leads to the proliferation and polarization of downstream T cells and the production of cytokines such as IFN-γ and IL-17A, which accelerate the progression of psoriasis." (PMID 38255845, 2024). "Since 2015, biologics targeting IL‐17A, IL‐17F, IL‐17RA, and IL‐23p19 have become available in Japan, thus expanding treatment options for patients with psoriasis." (PMID 39269210, 2024). "Usually, in most cases of psoriasis, inhibition of IL-17A alone results in marked improvement of the skin rash." (PMID 39519167, 2024). "Inspiringly, Bruton's tyrosine kinase inhibitor was reported to suppress IMQ‐induced psoriasis‐like inflammation through regulation of IL‐23/IL‐17A in innate immune cells, which enriches the recognition of psoriasis's pathogenesis and treatment idea." (PMID 38414294, 2024). "The lipidomic analysis results showed that anti-IL-17A mAb not only ameliorated skin lesions in psoriasis patients but also affected abnormal LCFAs metabolism." (PMID 38185620, 2024). "Two randomized clinical trials showed that secukinumab, a monoclonal antibody that targets IL-17A, mitigates psoriasis severity." (PMID 39184952, 2024). "From the six subtypes of the IL-17 family, IL-17A and IL-17F have been proven to be found both in psoriasis plaques as well as in unaltered skin, with IL-17A playing a central part in the pathogenesis of the disease." (PMID 38793117, 2024). "In a murine model of psoriasis, the blockage of IL-17A resulted in a significant reduction in oxidative stress and inflammation." (PMID 38540199, 2024). "The most extensively studied application is in the treatment of psoriasis, and IL-17A neutralization has been found to be an effective treatment for most psoriasis patients." (PMID 39456936, 2024). "This limitation of local production of IL-8 is likely to reduce the neutrophil influx in the skin, resulting in the lowered inflammatory reaction and limitation of the IL-17A positive feedback loop in psoriasis." (PMID 38672088, 2024). "Collectively, these results demonstrate that our co-assembly strategy effectively degrades IL-17A both in vitro and in vivo and displays potent anti-inflammatory activity, successfully ameliorating psoriasis symptoms in the IMQ-induced mouse model." (PMID 38396109, 2024). "Similar to the analysis results of LCFAs in the serum of psoriasis patients before and after anti-IL-17A mAb treatment, a total of 10 LCFAs were accurately detected in the serum of psoriasis-like mice." (PMID 38185620, 2024). "Currently, some clinical first-line drugs are used to treat psoriasis by activating autophagy through inhibition of the IL-17A." (PMID 39559368, 2024). "In human keratinocytes, HB-EGF and IL-17A synergistically induce IκBζ expression, which is essential for the induction of psoriasis signature genes in vitro, in a p38-MAP kinase-dependent manner." (PMID 38312837, 2024).
psoriasis (continued). "This inhibition resulted in a significant decrease in key inflammatory cytokines (Il1b, Il6, Il12b, Il17a, Il22, and Tnf) that are critical in psoriasis’ pathogenesis." (PMID 39335596, 2024). "The pathogenesis of psoriasis is complex and known pathogenic factors include TNF-α, IL-23, IL-17A, and so on." (PMID 38695018, 2024). "The compound provided a dose-dependent decrease in ex vivo-stimulated IL-17A levels in the blood, significantly reduced inflammation in mice collagen-induced arthritis and psoriasis models, and showed an acceptable clinical safety profile." (PMID 37238999, 2023). "Recent studies indicate that in psoriasis, IL-23 is required for the survival of Th17 and Tc17 cells, which are effector T cells that produce IL-17A." (PMID 38139369, 2023). "A psoriasis risk variant in the TRAF3 interacting protein 2 (TRAF3IP2) gene has been shown to induce Th17 differentiation and IL17A secretion, which is potentiated in the presence of NETs." (PMID 37628670, 2023). "We recently used RT-PCR analyses of total skin from a randomized placebo-controlled clinical trial (ClinicalTrial.gov identifier: NCT03131570) to study psoriasis skin transcriptome modifications induced by systemic IL-17A blockade." (PMID 37781383, 2023). "The chronic inflammation and increased production of IL-6 and IL-17A in psoriasis influence adipocytes differentiation and their capability of adipokine and chemokine synthesis and increase in visceral and subcutaneous white adipose tissue (WAT)." (PMID 37762217, 2023). "In particular, the nanobody sonelokimab inhibition of both IL-17A and IL-17F is under clinical study for its efficacy and safety in patients with psoriasis." (PMID 37238999, 2023). "T cell activation, which associated with the secretion of proinflammatory cytokines drive the psoriasis, including interleukin (IL)-17A, tumor necrosis factor-α(TNF-α), interferon IFN-γ and IL-22." (PMID 37029373, 2023). "The expression of those IL-17-driven inflammatory mediators in suprabasal KCs was correlated with psoriasis severity and was downregulated by systemic IL-17A blockade." (PMID 37781383, 2023). "IL-17F is believed to be generally co-expressed with IL-17A (the two genes are at the same locus), but this concept is being challenged by more recent data, analyzing emigrating cells from psoriasis samples at a single cell level." (PMID 37283755, 2023). "The suppression of psoriasis-related, proinflammatory, and Th17-associated cytokines, such as tumor necrosis factor (TNF)-α, IL-17A, and IL-23, was observed in mice fed with Lactobacillus pentosus." (PMID 36902001, 2023). "Previous data have attested that among immune cells, IL17A-producing Th17 helper (Th17) cells play an important role in the progression of psoriasis." (PMID 37298949, 2023). "Currently, the IL23/Th17 axis plays a crucial role in the occurrence and development of psoriasis, especially due to the IL-17A and IL-17F proinflammatory cytokines, which are among the most often incriminated factors in pathogenesis." (PMID 37239484, 2023). "Adalimumab, an anti-TNF antibody, and secukinumab, an anti-IL-17A antibody, have been approved for psoriasis treatment." (PMID 37377955, 2023). "Monoclonal antibodies targeting IL-17, IL-17A/F, and IL-17R have been developed and put into clinical use, which has benefited patients with moderate-to-severe psoriasis." (PMID 36817423, 2023). "JQ1, which targets BRD4 and exhibits therapeutic utility in cancer, inhibited the proliferation of keratinocytes and modulated the RORC/IL-17A pathway in a mouse model of psoriasis-like inflammation." (PMID 37762693, 2023). "Recently, it was demonstrated that the proinflammatory cytokine IL17A has a functional role in the process of skin inflammation in BP, similarly to psoriasis." (PMID 37077669, 2023). "In particular, the transactivation of IL-17A, the most important cytokine in psoriasis pathology, was effectively inhibited by AuNCs treatment." (PMID 36839031, 2023).
psoriasis (continued). "In the pathogenesis of psoriasis, IL-17A and TNF-α jointly stimulate skin keratinocytes to release VEGFA, leading to pathological angiogenesis." (PMID 38203230, 2023). "Further analysis using single-cell and spatial data from psoriasis samples confirmed the expression of hub genes that had low expressions in psoriasis tissue but were up-regulated after anti-IL17A treatments." (PMID 37816883, 2023). "TNFα alone, or in concert with IL17A, acts mainly through the activation of NF-κB, a critical pro-inflammatory pathway in the development of psoriasis." (PMID 37351597, 2023). "IL-23 receptors are also be able to be induced by ROR-γt, leading to a Th17 polarization and production of IL-17A and IL-22, which further promote psoriasis." (PMID 37270497, 2023). "Cytokines that upregulated in psoriasis patients include TNF-α, IL-1β, IL-12, and IL-17A were also involved in the development of lung cancer, indicating that both psoriasis and lung cancer are closely involved with immune alteration." (PMID 36604675, 2023). "CBD-loaded LSNs significantly reduced the PASI score and acanthosis, as well as inhibited the IL-17A release compared to the control treatment groups, indicating a substantial improvement in psoriasis symptoms." (PMID 37836750, 2023). "The role of γδ T lymphocytes as the main source of IL‐17A at early stages of psoriasis has been established, both in murine and human models." (PMID 36925706, 2023). "Given the reduction in IL-17A production in psoriasis-like skin inflammation models, the expression of CD200R1 on skin cells was examined." (PMID 36623588, 2023). "It achieved this by reducing keratinocyte proliferation, skin inflammation, and the levels of systemic pro-inflammatory cytokines typically increased in psoriasis subjects, such as IL-17A, IL6, or G-CSF." (PMID 38248322, 2023). "The IL-23/IL-17 signaling pathway is important for the induction and pathogenesis of psoriasis, as evidenced by the efficacy of IL-17A and IL-23 inhibitors in treating patients with psoriasis." (PMID 37964882, 2023). "It has been demonstrated that Th17 cells and the expression of their effector cytokine, IL-17A, are increased in autoimmune diseases, including psoriasis, multiple sclerosis, and rheumatoid arthritis." (PMID 36643586, 2023). "Blockade of IL-17A function in inflammatory diseases such as psoriasis shows promise, but its application to the treatment of dengue or Zika remain unexplored." (PMID 37943879, 2023). "Our results also show that IL-17A (a critical proinflammatory cytokine in the pathogenesis of psoriasis) induced increased glycolysis, lactate production, and psoriasis-related factors, including the expression of CXCL1/2 and IL-1α/β, in mouse primary KCs." (PMID 37303600, 2023). "Inhibition of BET proteins has been shown to decrease the expression of RORC, IL-17A and IL-22, all of them important psoriasis pro-inflammatory factors, representing a potential new therapy for psoriasis." (PMID 37628670, 2023). "IL-17A plays a role in SpA manifestations related to the skin, joints and enthesis, as reflected by the suppression of disease activity seen with IL-17A inhibitors in psoriasis, PsA and AS." (PMID 36675382, 2023). "The matter is less clear for IL-17A, which is used as treatment target for psoriasis and ankylosing spondylitis." (PMID 37219933, 2023). "Th17-related cytokines, such as interleukin (IL)-17A and IL-17F, are significantly elevated in psoriasis." (PMID 36817423, 2023). "The purpose of the study was to find translational evidence that systemic IL-17A blockade promotes regulatory transcriptome modification in human psoriasis skin immune cell subsets." (PMID 37781383, 2023). "In psoriasis, characterized by the fibrotic evolution of skin lesions, miR-1266 and miR-146, which are known to regulate IL-17A synthesis, were increased in the sera of these patients, also in association with RA." (PMID 38202170, 2023).